RN7SL784P (RNA, 7SL, cytoplasmic 784, pseudogene)
Gene: Miscellaneous RNA gene on chromosome 17 (4,882,975 to 4,883,316, forward strand). Ensembl gene ENSG00000264113.
Homologues: Orthologues: chimpanzee Metazoa_SRP (94% identical), macaque Metazoa_SRP (51% identical). Paralogues in human: Metazoa_SRP (72% identical), RN7SL811P (72% identical), RN7SL134P (71% identical), Metazoa_SRP (70% identical), RN7SL774P (70% identical), RN7SL96P (70% identical), RN7SL154P (70% identical), Metazoa_SRP (69% identical), RN7SL474P (69% identical), RN7SL123P (68% identical), RN7SL163P (68% identical), RN7SL488P (67% identical), and 710 more.